TNF (tumor necrosis factor)
Diseases named in the same sentence as TNF in open-access papers (continued):
Sharing a sentence is not in itself a finding about the gene and the disease.
rheumatoid arthritis (continued). "Thus, iRhom2-deficient mice are largely protected from diseases involving excessively released soluble TNF, such as sepsis, rheumatoid arthritis, and lupus erythematosus glomerulonephritis." (PMID 40081988, 2025). "Additionally, a study involving endothelial cells from individuals with rheumatoid arthritis revealed that IL-17, in combination with TNF-α, induced coagulants and a pre-thrombotic phenotype, surpassing the inflammatory state." (PMID 40977724, 2025). "Curcumin has an ability to downregulate the expression of the IκBα gene, cyclooxygenase-2 gene (COX-2), prostaglandin E-2 (PGE-2), interleukin-1–6–8 (IL-1, IL-6, IL-8), and tumor necrosis factor-α (TNF-α) in synovial fibroblasts obtained from patients with rheumatoid arthritis." (PMID 41462709, 2025). "Pathway enrichment analysis of differentially epimutated genes revealed significant overrepresentation of key inflammatory pathways, including TNF-alpha signaling via NF-κB and TGF-beta signaling which has been previously implicated in JIA and rheumatoid arthritis." (PMID 40999368, 2025). "Besides, the studies have shown that IL-37 alleviates TNF-induced pyroptosis of rheumatoid arthritis fibroblast-like synoviocytes by inhibiting the NF-κB/GSDMD signaling pathway." (PMID 40704967, 2025). "Indeed, a TNF-α vaccine has been tested in rheumatoid arthritis patients (a “TNF kinoid” showing reduced disease activity)." (PMID 41012116, 2025). "Although anti-TNF-α mAbs in rheumatoid arthritis may save long-term expenses by postponing disability, comparable advantages are lacking in AD, where therapy results remain ambiguous." (PMID 40507795, 2025). "TNF‐α, a key cytokine in inflammatory processes, stimulates fibroblasts to produce matrix metalloproteinases, which degrade the extracellular matrix in both rheumatoid arthritis and periodontitis." (PMID 41041963, 2025). "In addition, an intervention study with rheumatoid arthritis demonstrated that vitamin B6 supplementation was able to suppress IL-6 and TNF-alpha production." (PMID 40255391, 2025). "The therapeutic use of anti-TNF monoclonal antibodies, such as the TNF inhibitor, etanercept, is currently approved for the treatment of autoimmune diseases, such as Crohn’s disease and rheumatoid arthritis." (PMID 40243751, 2025). "For instance, in rheumatoid arthritis and psoriatic arthritis, the combination of biologics targeting different inflammatory pathways (e.g., TNF inhibitors with IL-17 or IL-6 blockers) has shown clinical potential in refractory cases, despite limited safety data." (PMID 41488677, 2025). "TNF-α is a core pro-inflammatory factor in arthritis (especially rheumatoid arthritis)." (PMID 41458513, 2025). "Individuals diagnosed with rheumatoid arthritis frequently report morning joint stiffness, a symptom that has been correlated with elevated circulating levels of pro-inflammatory cytokines such as tumor necrosis factor and interleukin-6 during the early morning hours." (PMID 40559115, 2025). "TNF-α can also elevatethe expression and enzymatic activity of protein phosphatase 1 inthe inflamed synovium, promoting the dephosphorylation of the Ser418site in Treg cells generated from rheumatoid arthritis, impairingTreg cell function." (PMID 40047620, 2025). "TNF is widely recognized for its role in the pathogenesis of arthritis in both patients and mouse models, and TNF‐blocking therapies remain among the first‐line treatments for rheumatoid arthritis." (PMID 40977146, 2025). "TNF-α is central to the pathogenesis of inflammatory diseases, such as rheumatoid arthritis (RA)." (PMID 40165960, 2025). "Recent evidence suggests that Ouabain can inhibit the secretion of pro-inflammatory cytokines, such as tumor necrosis factor-alpha (TNF-α) and interleukin-6 (IL-6), in macrophages, thereby mitigating inflammatory responses in conditions like rheumatoid arthritis and multiple sclerosis." (PMID 40851957, 2025).
rheumatoid arthritis (continued). "In rheumatoid arthritis (RA), 30%-40% of patients experience treatment failure with TNFα antagonists, including primary non-response, secondary loss of response, or adverse side effects." (PMID 41346622, 2025). "The ORAL Surveillance trial, which enrolled rheumatoid arthritis (RA) patients aged ≥50 with pre-existing cardiovascular risk factors, found a higher incidence of MACEs in those treated with tofacitinib (5 or 10 mg twice daily) compared with those on TNF inhibitors (HR: 1.33; 95% CI: 0.91–1.94)." (PMID 41003121, 2025). "Therefore, it is of interest to investigate the expression of inflammatory cytokines (TNF-α, IL-1, IL-6, and IL-17) in patients with rheumatoid arthritis (RA)." (PMID 41907960, 2025). "TNF-α blockers are a type of drug employed in the treatment of multiple inflammatory and autoimmune diseases, and are mainly applied in the first-line treatment of rheumatoid arthritis." (PMID 40351429, 2025). "Studies have shown that quercetin can effectively reduce the morning stiffness, morning pain, and post-activity pain of patients with rheumatoid arthritis, significantly improve clinical symptom scores, and reduce the levels of inflammatory factors such as TNF-α." (PMID 40771814, 2025). "Tumor necrosis factor (TNF) is an immunomodulatory cytokine that plays a critical role in the regulation of immune responses, particularly in chronic inflammatory conditions such as rheumatoid arthritis, inflammatory bowel disease, and muscular dystrophies." (PMID 41230865, 2025). "Enrichment analysis indicated that the common genes were primarily connected to KEGG pathways such as the TNF signalling pathway, rheumatoid arthritis, cytokine–tokine receptor interaction, chemokine signalling pathway, IL‐17 signalling pathway and the NF‐kappa B signalling pathway." (PMID 39993958, 2025). "Given the encouraging outcomes observed with [99mTc]Tc-anti-TNF-alpha scintigraphy in assessing active inflammation in other diseases, such as rheumatoid arthritis, ankylosing spondylitis, Graves’ ophthalmopathy, and more recently in psoriatic arthritis, we aim to evaluate its application in HS." (PMID 40872580, 2025). "Similarly, TNF-α inhibitors such as Infliximab, Adalimumab, and Etanercept, widely used in the treatment of autoimmune diseases such as rheumatoid arthritis, can help reduce inflammation by inhibiting TNF-α signaling." (PMID 40401196, 2025). "Regulation of the Wnt signalingpathwayin rheumatoid arthritis involves interleukin-1 beta,tumor necrosis factor alpha, and interleukin-6, which activatethe expression of the WNT5A gene encoding the WNT5Aprotein – a ligand of FZD receptors participating in the noncanonicalWnt pathway." (PMID 41536794, 2025). "Thus, TNF blockers are used in rheumatoid arthritis, ankylosing spondylitis, ulcerative colitis, Crohn’s disease, and psoriatic arthritis." (PMID 40427602, 2025). "B lymphocytes in the peripheral blood of rheumatoid arthritis patients may release many cytokines, including TNF-α, IFN-γ, IL-6, IL-1β, IL-17, and IL-10, which facilitate bone deterioration." (PMID 41127878, 2025). "Tumor necrosis factor-alpha (TNF-α) inhibitors are a cornerstone in the management of chronic immune-mediated diseases, including rheumatoid arthritis, ankylosing spondylitis, psoriatic arthritis, plaque psoriasis, and, in selected cases, refractory sarcoidosis." (PMID 41107632, 2025). "Additionally, by activating the JNK signaling pathway, PSVII has been shown to suppress the expansion of fibroblasts in rheumatoid arthritis, alleviating symptoms and reducing levels of TNF-α, IL-6, and IL-1β." (PMID 40405066, 2025). "AAAs develop in approximately 13% of patients with rheumatoid arthritis, spondyloarthritis, or inflammatory bowel disease who are treated with TNF inhibitors, substantially reducing the clinical response, while concomitant immunosuppressive therapy markedly lowers AAA formation." (PMID 41199323, 2025).
rheumatoid arthritis (continued). "In this hypothesis article, we suggest a mechanism that produces a TNF‐α hypersecreting state in rheumatoid arthritis patients, which may also explain the exaggerated inflammatory response in urban compared to rural areas of sub‐Saharan Africa." (PMID 40489164, 2025). "In general, for peripheral SpA the differential diagnosis may include septic arthritis, osteoarthritis, gout, rheumatoid arthritis, psoriatic arthritis, fibromyalgia, and medication side effects (for example, a lupus-like reaction to an anti-TNF agent)." (PMID 40658153, 2025). "While YWHAZ promotes inflammation resolution in rheumatoid arthritis via regulatory T cells and M2 macrophages, our data show patient uEVs induce robust NF-κB activation comparable with TNF-α, suggesting context-dependent pro-inflammatory effects in refractory IC/BPS." (PMID 41516009, 2025). "Notably, lipid and atherosclerosis, the TNF signaling pathway, rheumatoid arthritis, and the IL-17 signaling pathway were significantly enriched." (PMID 39440769, 2025). "Finally, Jones and colleagues reported in their study with AIA rats that MG-132 inhibited the MMP-2 activity induced by the combination of TNFα and IFNγ in rheumatoid arthritis synovial fibroblasts (RASFs)." (PMID 40243560, 2025). "We found that itaconate is a TNF-α responsive metabolite significantly elevated in the serum and synovial fluid of rheumatoid arthritis patients and we demonstrated that itaconate is primarily produced by inflammatory macrophages rather than osteoclasts or osteoblasts." (PMID 40500265, 2025). "In rheumatoid arthritis, patients significantly altered serum cytokines, reducing TNF-α, IL-15, and RANTES (Regulated on activation, normal T expressed and secreted), while increasing IL-10, which correlated with clinical improvement, especially in treatment responders." (PMID 41044647, 2025). "While TNF inhibition has demonstrated success in treating autoimmune diseases, such as rheumatoid arthritis or psoriasis, patients undergoing anti-TNF therapy for these indications are at risk for developing demyelinating CNS lesions, indicating a disease-specific effect." (PMID 39794498, 2025). "Biologic therapies targeting TNF-α and IL-6 in rheumatoid arthritis may provide dual benefits, improving both joint-related disease activity and neuropsychiatric symptoms such as depression, fatigue, and cognitive dysfunction." (PMID 40943274, 2025). "The most distinguished research in the field of precision medicine for rheumatoid arthritis is exemplified by the R4RA (rituximab vs. tocilizumab in anti‐TNF inadequate responder patients with rheumatoid arthritis) study, a clinical trial underpinned by synovial biopsy." (PMID 40269471, 2025). "In addition to this, it has been reported that soluble TNF-α is increased in ankylosing spondylitis patients > 2 months with Etanercept therapy and for rheumatoid arthritis > 2 months." (PMID 40981186, 2025). "In the realm of inflammatory pain, research has demonstrated the efficacy of extracts derived from genera such as Sargassum, Laminaria, and Ecklonia in significantly downregulating the expression of pro-inflammatory cytokines, including IL-6 and TNF-α, in experimental models of rheumatoid arthritis." (PMID 40710495, 2025). "It is important to emphasize that the recommendation is based on this pivotal study which involved patients with NYHA class III and IV heart failure who did not have concomitant inflammatory diseases such as ulcerative colitis or rheumatoid arthritis, diseases known for their elevated TNF-α levels." (PMID 41155452, 2025). "This study sheds light on the serum concentration during a flare and immunogenicity of TNF inhibitors in rheumatoid arthritis patients with a well-controlled disease who are tapering and stopping their DMARDs and provides insights for measuring drug concentration in daily practice." (PMID 41155623, 2025).
rheumatoid arthritis (continued). "Furthermore, in rheumatoid arthritis patients refractory to anti-TNF agents, tocilizumab demonstrated efficacy and SAEs comparable to those of rituximab." (PMID 41424786, 2025). "In contrast, pateclizumab, a specific blocker of LTA, showed much-reduced efficacy compared to the TNF blocker adalimumab in a clinical trial for rheumatoid arthritis, which may call into question the risky role of LTA in bone." (PMID 40224485, 2025). "A controlled study based on 25 patients within the age range of 40–82 years indicated that the risk of thrombosis would decrease when patients were exposed to TNF-α blocker drugs.And it is consistent with the analysis results of a study involving more than 40 rheumatoid arthritis(RA) patients." (PMID 40351429, 2025). "A meticulously planned synthesis process was employed to create a lipid nanoparticle system capable of simultaneously encapsulating hydroxychloroquine, a commonly utilized small-molecular drug in rheumatoid arthritis treatment, and siRNA directed against TNF-α." (PMID 39861693, 2025). "Similarly, a clinical trial reported PRP was an effective therapy in treating rheumatoid arthritis patients through its down-regulating effect on inflammatory cytokines, such as IL-1β and TNF α." (PMID 39906617, 2025). "Others have also shown a role for ephrin B1 and TNFα in rheumatoid arthritis models." (PMID 38501146, 2024). "Clinical studies have also indicated that VNS might be beneficial against rheumatoid arthritis owing to a reduction of TNF-α release ex vivo and might lead to improvements in disease severity." (PMID 39881804, 2024). "Epidemiological studies suggest that synovial tissue and activated circulating immune cells in rheumatoid arthritis release pro‐inflammatory cytokines such as TNF‐α and IL‐6, which directly lead to systemic inflammation, a pro‐inflammatory state and the risk for cardiovascular disease." (PMID 39494478, 2024). "This gene is involved in TNF-α signaling and is overexpressed in rheumatoid arthritis." (PMID 38601075, 2024). "Interestingly, the use of tocilizumab, an anti-IL-6 therapy, has been shown to be associated with a rapid QTc shortening in patients with rheumatoid arthritis, which was correlated with the decrease in both CRP and tumor necrosis factor (TNF)-α levels." (PMID 38337348, 2024). "They showed that blocking TNF in cultures of human rheumatoid tissue stopped the production of interleukin-1 (IL-1β) and other cytokines, suggesting that TNF is a “master regulator” in rheumatoid arthritis." (PMID 39584990, 2024). "For example, nVNS could enhance the effects of TNF inhibitors in rheumatoid arthritis or reduce the necessary dosages of corticosteroids in asthma, thus minimizing drug-related side effects and improving overall patient outcomes." (PMID 39605787, 2024). "Given the role of NRDC in the activation of TNF-alpha, which was validated in some inflammatory disease models including rheumatoid arthritis and steatohepatitis, NRDC may aggravate the pathology of ACS by enhancing inflammation." (PMID 38233578, 2024). "This is supported by studies reporting that exposure of human ADSCs to synovial fluid from patients with rheumatoid arthritis or plasma from patients with graft-vs.-host disease, which contain picogram levels of multiple inflammatory cytokines such as TNF-α, exerts better immunomodulatory effects." (PMID 39176394, 2024). "Approved treatments for rheumatoid arthritis that may work by inhibiting angiogenesis include TNF, IL-1β, and IL-6 inhibitors, thalidomide, and Cox-2 inhibitors." (PMID 38671436, 2024). "It is investigated that the anti-inflammatory properties of mianserin, a serotonin (5HT) receptor antagonist, was able to inhibit the endosomal TLR8 in primary human cells and inhibited the spontaneous release of TNF and IL-6 from rheumatoid arthritis synovial membrane cultures." (PMID 39234104, 2024).
rheumatoid arthritis (continued). "In line with this assumption, earlier studies described that the IL-18-induced VCAM-1 protein expression in rheumatoid arthritis synovial fibroblasts and the TNF-α-induced VCAM-1 expression in human cardiac fibroblasts are controlled by the Src/PI3K/Akt signaling pathway." (PMID 39768198, 2024). "These elevated levels may reflect the synovial tissue macrophages, which are recognized as pro-inflammatory cells previously shown to have a key role in rheumatoid arthritis by producing TNF, in turn driving chronic pathology." (PMID 38802975, 2024). "A retrospective analysis of patient with TNF inhibitor-induced psoriasis also yields consistent findings, indicating that infliximab is the predominant triggering agent, while Crohn's disease and rheumatoid arthritis are the most common primary conditions." (PMID 38347543, 2024). "Studies looking at diabetes in patients with rheumatoid arthritis have shown that DMARDs such as TNF inhibitors, hydroxychloroquine, and methotrexate may improve glycaemic control." (PMID 39261370, 2024). "Abnormal or excessive production of TNF can induce a variety of immune-mediated inflammatory diseases such as rheumatoid arthritis (RA), inflammatory bowel disease (IBD) psoriatic arthritis (PsA), psoriasis (PS) ankylosing spondylitis (AS), and non-infectious uveitis (NIU)." (PMID 38926254, 2024). "Etanercept is an anti-TNF medication approved for the management of rheumatoid arthritis." (PMID 39439890, 2024). "The inflammatory targets that mediate rheumatoid arthritis mainly include (TNF, PTPN11, IL6, etc.); the main targets that mediate RA oxidative stress are NOS3; the targets that mediate the destruction of extracellular matrix tissue in RA mainly include (MMP9, MMP2, ANXA5, etc.)." (PMID 38238321, 2024). "However, TNF-α monoclonal antibodies are commonly used to treat conditions like rheumatoid arthritis, ankylosing spondylitis, or psoriasis, with varied effects on kidney function." (PMID 38740765, 2024). "Anti-TNF-α agents play a significant part in therapy of various inflammatory disorders such as rheumatoid arthritis, ankylosing spondylitis, psoriatic arthritis, plaque psoriasis, juvenile idiopathic arthritis, ulcerative colitis, Crohn’s disease, and sarcoidosis." (PMID 39180528, 2024). "Currently, multiple guidelines recommend prompt initiation of treatment with TNF inhibitors in individuals with rheumatoid arthritis, psoriatic arthritis, and ankylosing spondylitis who exhibit an inadequate response to standard or other conventional treatments." (PMID 39070789, 2024). "A study showed 216 reported cases of suspected TNF inhibitor-induced or -exacerbated psoriasis, which occurred more frequently with infliximab and was most prevalent in the first year of treatment for Crohn's disease and rheumatoid arthritis." (PMID 38347543, 2024). "Moreover, TNF-α produced by macrophages in the synovial cells of rheumatoid arthritis patients was suppressed by ginsenoside Rc by suppressing the AP-1 activation." (PMID 38586374, 2024). "Taken together, these data lend support to the notion that clinically prescribed IL1 and TNF inhibitors for inflammatory conditions (e.g. rheumatoid arthritis) could be used during pregnancy to reduce IL6 trans-signaling and IUI induced adverse consequences." (PMID 38895127, 2024). "Additionally, TNF-α also upregulates A3 adenosine receptor expression, as it is elevated in PBMCs from patients suffering from rheumatoid arthritis, psoriasis, and Crohn’s disease, whereas A3 adenosine receptors are low or absent in cells from healthy donors." (PMID 38891997, 2024). "Moreover, we applied our system to produce ozoralizumab, a multispecific VHH that binds to human TNF-α and albumin and are marketed as a rheumatoid arthritis drug." (PMID 39161731, 2024).